TRAF6 (TNF receptor associated factor 6)
Diseases named in the same sentence as TRAF6 in open-access papers (continued):
Sharing a sentence is not in itself a finding about the gene and the disease.
infection (continued). "For Toll signaling pathway-related genes, the expression of the Toll9, TNF receptor associated factor 6 (TRAF6), Myd88, and Pellino genes was upregulated in R. chinensis after infection with SM1, while the expression of Spatzle was downregulated in this study." (PMID 35323524, 2022). "In conclusion, our results show that ALV-A (HB2015012) infection increased the expression level of A20 and inhibited the ubiquitination of TRAF6, resulting in its upregulation." (PMID 36298765, 2022). "A52 interacts with TRAF6 through the TRAF6-encoded TRAF domain and has been shown to enhance virulence in murine intranasal models of infection." (PMID 36145493, 2022). "In T. gondii infections, TRAF6 contributes to a host protective immunity by regulating the production of pro-inflammatory cytokine IL-12, which is essential to control the infection, and vacuole-lysosome fusion, a fundamental step during infection." (PMID 35702995, 2022). "The results showed that at both mRNA and protein levels, HUWE1 and TRAF6 were decreased during the infection." (PMID 35107378, 2022). "In response to H1N1 or H3N2 infection, on day 5 post infection there were also similar expression patterns of Mavs, Traf3, and Traf6 detected in young lung." (PMID 34829979, 2021). "Upon infection with an RNA or DNA virus, USP25 associates with TRAF3 and TRAF6 and protects TRAF3 and TRAF6 from virus-induced proteasome-dependent or independent degradation." (PMID 34249948, 2021). "Mechanistically, MYSM1 translocated to the cytoplasm upon infection to remove K63-linked ubiquitin chains from TRAF3 and TRAF6, terminating type I IFN induction, before being rapidly degraded itself." (PMID 33808506, 2021). "Real-time PCR revealed the expression of RANKL and TRAF6 was significantly increased after infection with L. monocytogenes on neutrophils isolated from mouse bone marrow." (PMID 32889432, 2020). "At later stages of infection, SopB relocates to the Salmonella-containing vacuole upon monoubiquitination on multiple lysine residues by the host E3 ligase TRAF6, promoting intracellular bacterial replication." (PMID 31848284, 2019). "In contrast to TGFβ, TRAF6 recruitment to the ALK4/ActRII complex was significantly decreased early after infection although it was restored at 18 hpi." (PMID 30891432, 2019). "We noticed that some studies have shown that protein levels of MAVS, or TRAF3, or TRAF6 were downregulated to some extent after infection with different viruses." (PMID 29734366, 2018). "For example, the deubiquitinase A20 and CYLD are induced in response to cytokine treatment and infection and have been found to inhibit NF-кB by hydrolyzing K63-linked polyubiquitin chains on key NF-кB signaling molecules, such as RIP1, TRAF6, and TAK138." (PMID 30348973, 2018). "Of note, the expression of both TRAF3 and TRAF6 were unaffected by the infection (expressed below the threshold of detection)." (PMID 28993767, 2017). "The Levels of TRAF6 remains unchanged in HT-29 cells but degraded in the late stage of infection only in RD cells." (PMID 27007979, 2016). "To better understand the therapeutic mechanism of MJWQH in mice infected with H1N1 virus, we measured the expressions of TLR7, MyD88, TRAF6, p65, p-p65, IκB-α, and p-IKKα/β in lung tissues on days 2 and 4 after infection by using Western blot analysis." (PMID 26089947, 2015). "Overexpression of IRAK-4 or TRAF6 resulted in stimulation of NF-κB in zebrafish cells and TRAF6 transcript levels increased following infection with snakehead rhabdovirus." (PMID 26184332, 2015). "The transcriptional levels of MyD88, IRAK-1, and TRAF-6 were significantly increased in mice infected with either P. yoelii 17XL or 17XNL compared to control mice at one, three and five days post-infection." (PMID 22463100, 2012). "The change pattern of transcription levels of MyD88, IRAK-1, and TRAF-6 of macrophage was consistent with its response to pRBC lysate after infection with either strain." (PMID 22463100, 2012).
infection (continued). "Like LMP-1 of the Epstein-Barr virus, UL144 activates TNFR-activated factor 6 (TRAF6), leading to NF-κB (nuclear factor kappa-light-chain-enhancer of activated B cells) activation in early infection." (PMID 21669005, 2011). "Within siNC treated groups, both MyD88 and TRAF6 were consistently down-regulated with SE challenge (-2.34 - fold at 1 h and -2.37 - fold at 4 h, post-infection for MyD88, and -1.60 - fold at 1 h and -1.45 - fold at 4 h post-infection for TRAF6)." (PMID 21637513, 2009). "Induction of the nuclear DNA binding activity of NF-κB was abrogated in Traf6−/− MEF cells in response to infection with SeV Cm or NDV." (PMID 19479062, 2009). "In contrast to that observed in TRAF3−/− MEF, levels of mRNA and secreted IFN-β in TRAF6−/− cells supernatants were equivalent to wild type cells at 24 hours post infection (P>0.2) but slightly reduced at 48 hours (∼2-fold decrease, P<0.0001)." (PMID 19798431, 2009). "Treatment with CNP-miR146a four hours after infection resulted in significantly decreased relative gene expression of TRAF6 (p = 0.01), NF-κB (p = 0.003), IL-6 (p = 0.01), MIP-2 (p = 0.005), IL-1β (p = 0.01), and TNFα (p = 0.003) compared to untreated, MRSA-infected lungs." (PMID 37765178, 2023). "ZIKVMR766 also induced higher expression of TRAF6 early after infection compared to ZIKVPE243." (PMID 37376550, 2023). "The results showed that H37Rv infection elevated TRAF6 expression in RAW264.7 cells." (PMID 38016969, 2023). "Nevertheless, even though T cells lacking TRAF6 cause autoimmune inflammation, it is unclear in how far they would be able to mount a productive adaptive immune response upon infection." (PMID 36761777, 2023). "TRAF6 also contributes to early steps in the process of autophagy, which is induced in response to stress stimuli including growth factor depletion, nutrient deprivation and infection." (PMID 34298830, 2021). "TRAF6 also mediates Ecsit ubiquitination and nuclear translocation to facilitate the transcription of ALFs, which affect hemolymph microbiota homeostasis in response to pathogens infection." (PMID 34379706, 2021). "We observed decreased TRAF6 expression upon infection with HIV-1 at the gene expression level." (PMID 32117283, 2020). "Similar to IRAK4, the notable changes in TRAF6 were observed 24 hours after infection." (PMID 31871425, 2019). "Similarly, infection with TRAF6 interfering virus increased the percentage of S phase, and reduced cell apoptosis in NP cells." (PMID 29038477, 2017). "Here we demonstrate that the host proteins ALPK1, TIFA and TRAF6 act sequentially to activate the transcription factor NF-κB and regulate the production of chemokines in response to infection by the pathogens Shigella flexneri, Salmonella typhimurium and Neisseria meningitidis." (PMID 28222186, 2017). "One striking difference that exists between our findings and those of Wies and colleagues is that we demonstrate that PP1-γ associates with TRAF6 and IKKγ under basal conditions in the absence of infection." (PMID 24586659, 2014). "In previous studies, importance of TRAF-6 activation has been shown in infection by various RIG-I sensed RNA viruses such as vesicular stomatitis virus, Newcastle disease virus, encephalomyocarditis virus, Sendai virus and also in respiratory syncytial virus, but not in CHIKV infection." (PMID 24086645, 2013). "We hypothesized that TRAF6 proteasomal degradation is a downstream target for lipoxin-mediated control of pro-inflammatory responses during in vivo infection." (PMID 22693634, 2012). "Indeed, TRAF6 was detected at 30 and 60 minutes post-infection in the Triton X-100 insoluble pellet of γHV68-infected MEFs, but not in that of mock-infected MEFs." (PMID 22110409, 2011). "Plaque assays and multi-step growth curves of γHV68 lytic infection showed that deficiency in TRAF6, IKKγ, and IKKβ, but not deficiency in the closely related IKKα, recapitulated phenotypes of MAVS deficiency." (PMID 20686657, 2010).
infection (continued). "However, despite this inversion at 24 h after infection, the amount of IFNα protein secreted from Traf6−/− MEF cells was significantly higher than that from Traf6−/− MEF cells in response to NDV infection at 24 h post-infection and thereafter." (PMID 19479062, 2009). "Therefore, TRAF6 has been shown to be essential for sufficient antiviral responses to infection with four different RNA viruses, leading to the conclusion that TRAF6 is involved in RLH signaling." (PMID 19479062, 2009). "However, during L. europaeus GI.1 infection we noted a downregulation of TRAF6 was a 2-fold reduction (p = 0.02) compared to the control, while during L. europaeus GI.2 genotype infection a downregulation of TRAF6 was 2.9-fold reduction (p = 0.005 vs. control)." (PMID 39273479, 2024). "MiR-146a, by targeting TRAF6, also decreased the conversion of the microtubule-associated protein light-chain 3-I (LC3-I) to LC3-II, as well as negatively regulating the autophagy process of A549 cells and THP-1 cells during DENV2 infection, thus contributing to efficient viral replication." (PMID 36142450, 2022). "One intriguing possibility is through the TRAF6-mediated K-63 ubiquitination and nuclear localization of hnRNPA1 during innate immune activation; if the activity of TRAF6 is inhibited during infection hnRNPA1 activity could drop, leaving TRA2-β pre-mRNA vulnerable to inclusion of the poison exon." (PMID 35127560, 2021). "In addition to revealing the TRAF-2 and TRAF-6 ubiquitin ligase complexes, which have known roles in immune signaling during infection, this analysis identified ubiquitin ligase complexes, including CUL3, RBX1, and MDM2, that have not been previously implicated in Mtb pathogenesis." (PMID 31951200, 2020). "It is also relevant to consider potential interplay between miRNAs regulating the same pathway: miR-146a also targets TRAF6 and is induced following infection and therefore could play a more prominent role in negatively regulating TRAF6-dependent antiviral responses at later stages of infection." (PMID 28380049, 2017). "This hypothesis was tested by determining whether TIFA and TRAF6 co-localized after infection." (PMID 28222186, 2017). "However, transcription of intracellular signalling molecules MyD88, IRAK-1, and TRAF-6 was significantly up-regulated in peritoneal macrophages from mice infected either with P. yoelii 17XL or P. yoelii 17XNL at one, three and five days post-infection." (PMID 22463100, 2012). "Once trapped in this state, our model predicts that cells may be slow or unable to return to normal because these bacteria are also capable of directly activating the IRAK/TRAF6 module thus triggering vicious cycles of infection, ineffective bacteria clearance, and chronic inflammation." (PMID 19390631, 2009). "The results showed that high level-/long time-H37Ra infection downregulated the phosphorylation level of NF-κB as well as the expression of TLR4, TRAF6, and MyD88." (PMID 40502714, 2025). "The expression of Myd88, IRAK4, and TRAF6 mRNA in both WT and WUCI significantly increased and reached their peak when they were infected with A. hydrophila on day 1 post-infection." (PMID 40298788, 2025). "Although deleting I177L almost entirely blocks ASFV-mediated inflammation, we still detected TRAF6 and TAK1 ubiquitination levels in the ASFV-ΔI177L infection group." (PMID 40135893, 2025). "E. coli‐infection induced upregulation of IRF7 and phosphorylation of IRF7 via activating MyD88‐IRAK4‐IRAK1/TRAF6 axis." (PMID 39166412, 2024). "Particularly, mixed-species infection increased the expression of TLR2/4, Nox2/4, and Toll/IL-1R domain-containing adaptor proteins such as MyD88 and TRAF6." (PMID 38700089, 2024). "Meanwhile, we found that the infection time and MOI of TRAF6 differentially expression is different in BCG-infected RAW264.7 cells and BMDMs, which indicates that the expression of the same protein in different cell lines is widely different." (PMID 38016969, 2023).
infection (continued). "The Poly (I:C)-induced cells, incubated with high multiplicity of infection (MOI = 3) of the PDCoV, significantly downregulated the expression of RIG-I and TRAF6 and repressed the transcription of RIG-1, IRF7 and IRF3." (PMID 36982944, 2023). "Significant differences (p < 0.05) in the expression of only STAT1, STAT4, TRAF6, and NFKB1 factors were observed for the different types of macrophages, at different times of infection." (PMID 35774406, 2022). "ii) TLR3, a receptor for viral dsRNA, displayed a strong reduction in influenza virus and icMERS infection, while TICAM1, TRAF1, TRAF2, TRAF3 and TRAF6, adaptors responsible for TLR3, changed in an opposite direction with TLR3." (PMID 34248940, 2021). "Differential activation of autophagy and MTORC1 by SQSTM1/p62TRM, TBK1, TRAF6 and RALB, which are among the prominent molecules involved in both pathways, needs to be studied further in disease and/or infection-relevant settings." (PMID 32627660, 2021). "For the TLR pathway, one TLR homolog, the adaptor molecule MyD88, TRAF6, kinase IRAK4 and two transcription factors IкB-α and NF-кB were all significantly upregulated after 6 h and 12 h of infection." (PMID 32276269, 2020). "This signaling step is also affected by HCMV-UL48 along with the STING and TRAF6 mediated IFN response, suggesting that the viral deconjugases may act at multiple levels of the signaling cascade, possibly reflecting the need to adapt to different susceptible targets and types of infection." (PMID 32226432, 2020). "Mechanistically, UL144 complexes with TRAF6 in perinuclear regions of the cell to enable NFκB transcription factor translocation and binding, and siRNA targeting UL144, TRAF6, or NFκB all ablate the downstream CCL22 expression induced by infection." (PMID 30134546, 2018). "While infection remained comparable, this independent approach confirmed a dramatic inhibition of IL-8 after S. flexneri ΔvirG infection of cells depleted for TIFA and TRAF6." (PMID 28222186, 2017). "Phosphorylation of IRF3 triggered by SeV-infection was greatly inhibited and the production of IFN-β was blocked when TRAF3 or TRAF6 was deleted." (PMID 26456228, 2015). "Another intriguing possibility comes from work showing that EV71 modulates the levels of TRAF6 and IRAK1 during infection." (PMID 26437794, 2015). "Conversely, a number of adaptor genes involved in TLR3 signaling such as TRIF, TRAF6 and RIP1 were up-regulated within 24–48 hours of infection." (PMID 25826356, 2015). "Of note, although the infection of BCG augmented the expression of TLR6 and TRAF6 at protein levels, the expression levels were dramatically repressed in BCG-infected cells that were transfected with miR-124 mimic (p<0.05)." (PMID 24705038, 2014). "For this purpose we evaluated the expression of TLR-2, MyD88, IRAK4, TRAF6, and TIRAP in macrophages at 48 hr after infection with H37Rv, BCG, H37RvΔRD-1 or H37RvΔESAT-6." (PMID 24475192, 2014). "Treatment with ASA early in infection not only ablated TNF-α release from spleen but also increased SOCS-2 and reduced TRAF6 expression." (PMID 21347238, 2011). "Our results demonstrate a clear inactivation of the TRAF5 and TRAF6 genes when infection occurs after immunization, in contrast to infection without prior vaccination." (PMID 40136419, 2025). "At 24h post-infection, miR-1236-3p-m and si-TLR4 significantly reduced the expression of TLR4 and downregulated the phosphorylation level of p65, as well as the expression of TRAF6 and MyD88." (PMID 40502714, 2025). "In tick-borne flaviviruses (TBFVs) infection, the viral nonstructural 3 (NS3) protein interacts with TRAF6 during infection to support TBFV replication." (PMID 38241362, 2024). "As the infection progresses, MAP grows within granulomas but the upregulation of the bta-miR-215 and bta-miRNA-146a would control the activation of an excessive pro-inflammatory response by targeting BMX and TRAF6, respectively." (PMID 38167436, 2024).
infection (continued). "Although expression of Traf3 and Traf6 moderately suppressed infection, they did not alter the increase in IAV production from Usp25−/− cells." (PMID 37683630, 2023). "Whole lung tissue was collected 24 h after infection and processed for RT-qPCR to evaluate for relative gene expression of proinflammatory genes IRAK1, TRAF6, NF-κB, IL-6, MIP-2 (murine IL-8 analog), IL-1β, and TNFα as these cytokines outline the pathway along which miR146a functions." (PMID 37765178, 2023). "Infection with P. gingivalis dramatically increases A20 expression in innate immune cells, which subsequently interacts with TRAF1 and TRAF2 to form a ubiquitin-editing complex to prevent K63 polyubiquitin chain synthesis by TRAF6." (PMID 35588785, 2022). "In addition, we found that apoptosis and ROS levels were upregulated when HUWE1 and TRAF6 were silenced during WSSV infection, suggesting the regulation of HUWE1 and TARF6 in apoptosis and ROS production during the infection." (PMID 35107378, 2022). "TRAF6 was found to interact with IRAK1 and TAK1 after infection with different strains, but the binding of TRAF6 to IRAK1 or TAK1 was not different in RAW264.7 cells infected with rMS::pMV261 or rMS::pMV261-Rv0927c." (PMID 34531869, 2021). "Infection of cells with a number of various viruses including Hepatitis C virus (HCV), Coronaviruses (CoV) and the bovine herpes virus (BHV-1) leads to the degradation of TRAF6 to enable escape from host cell immune signaling by different decay pathways." (PMID 34298830, 2021). "In the current study, we reported that wild-type Mtb, but not the ∆choD strain, decreased the cytosolic IRAK4 and TRAF6 levels after prolonged (24 hours) infection." (PMID 31871425, 2019). "To assess whether IRAK4 and TRAF6 are functional targets for Mtb to the induction of IL-8 production, we incubated the macrophages with an IRAK1/4 inhibitor prior to the infection." (PMID 31871425, 2019). "The macrophages treated with siTRAF6 secreted significantly less IL-8 than did control macrophages without silenced TRAF6 in response to infection with the wild-type, ΔchoD, or complemented strain (by 62%, 65%, and 61%, respectively)." (PMID 31871425, 2019). "Therefore, during a short infection time, the IRAK4 and TRAF6 mRNA levels can be unaffected, then upregulated (24 hours), and finally downregulated after a prolonged infection time (48 hours)." (PMID 31871425, 2019). "To do this, we analyzed MyD88, TRAF6, IKKα, IKKβ, and phospho-IKKα/β (p-IKKα/β), which we found were not affected by infection, and LPS-induced IκBα degradation." (PMID 29440572, 2018). "The results showed that SeV infection had no obvious effect on the levels of both MAVS and TRAF6 mRNAs within 12 hr after infection." (PMID 29734366, 2018). "Similar results were obtained upon infection with wild-type bacteria as well as in HEK293 cells, showing that the contribution of TIFA and TRAF6 was not restricted to infections with the ΔvirG mutant or with HeLa cells." (PMID 28222186, 2017). "As expected, miR-146a did not alter mRNA level of TRAF6, but substantially reduced TRAF6 protein levels at 24 h and 48 h post-infection." (PMID 27025258, 2016). "While TRAF-6 expression was not altered at this time point of infection, the level of mRNAs corresponding to IL-6 and IFN-β were significantly upregulated in DENV-2 infected A549 cell cultures." (PMID 25962098, 2015). "However, significant alterations in the expression pattern of specific target genes (TRAF6, IRAK1 and IRAK2) were observed only after 32 hours of infection." (PMID 25083878, 2014). "Upon infection (TLR activation), the recruitment of TRAF6 into TNFR signalsome may play a critical role in amplifying TNF responses leading to un-controlled tissue damages." (PMID 24758719, 2014).